FSTL5 (follistatin like 5)
Synonyms: KIAA1263; DKFZp566D234
Tractability: Antibody: UniProt places it where antibodies can reach, with high confidence; UniProt predicts a signal peptide or a membrane-spanning region; its Gene Ontology location is reachable by antibodies, with medium confidence.
Gene: Protein-coding gene on chromosome 4 (161,383,897 to 162,164,005, reverse strand). Ensembl gene ENSG00000168843.
Subcellular location: Secreted
Gene Ontology:
Molecular function: protein binding; calcium ion binding
Biological process: cell differentiation; regulation of BMP signaling pathway
Cellular component: extracellular region
Genetic constraint (gnomAD): Loss-of-function variants: 20 observed, 38.12 expected, observed/expected ratio (o/e) 0.52, 90% interval 0.37 to 0.76. The upper end of that interval is the gene's LOEUF score, 0.76, which puts it in group 3 of 6, group 1 being the genes least tolerant of losing a copy. Missense variants: 623 observed, 635.45 expected, observed/expected ratio (o/e) 0.98, 90% interval 0.92 to 1.05. Synonymous variants: 243 observed, 225.1 expected, observed/expected ratio (o/e) 1.08, 90% interval 0.97 to 1.2.
Homologues: Orthologues: chimpanzee FSTL5 (99% identical), macaque FSTL5 (98% identical), dog FSTL5 (95% identical), rabbit FSTL5 (93% identical), pig FSTL5 (93% identical), mouse Fstl5 (91% identical), rat Fstl5 (91% identical), guinea pig FSTL5 (81% identical), tropical clawed frog fstl5 (77% identical), zebrafish fstl5 (70% identical). Paralogues in human: FSTL4 (56% identical), SPINK5 (12% identical), FSTL1 (11% identical), FST (8% identical), FSTL3 (6% identical), SPINK6 (2% identical).
Diseases named in the same sentence as FSTL5 in open-access papers:
FSTL5 is named in the same sentence as 19 diseases in open-access papers, as found by Europe PMC text mining. Sharing a sentence is not in itself a finding about the gene and the disease. The quoted sentences say what the papers report.
medulloblastoma (8 papers, 2012 to 2024). A malignant, invasive embryonal neoplasm arising from the cerebellum. "FSTL5 is associated with diseases such as medulloblastoma, schizophrenia, hepatocellular carcinoma, and colorectal cancer." (PMID 33562363, 2021). "Immunopositivity of FSTL5 identified a large group of patients at high risk across all medulloblastomas, but more importantly, also within Group 3 and 4 patients." (PMID 22358457, 2012). "FSTL5 immunopositivity serves as a marker for poor prognostication in both Group 3 and Group 4 medulloblastomas." (PMID 30944042, 2019). "The positional candidate gene, FSTL5, has been previously identified as a prognostic marker in human patients with medulloblastoma." (PMID 26509595, 2015). "FSTL5 is a secretory glycoprotein and is known to be a prognostic biomarker for medulloblastoma." (PMID 39342078, 2024). "In contrast to oncogenes, tumour suppressor genes such as FSTL5 were homogeneously lost in LFS medulloblastomas throughout the tumour tissue, but not in the sporadic medulloblastomas." (PMID 39609432, 2024). "Studies have shown an array of functions for FSTL5 in the human body, ranging from inhibiting the progression of hepatocellular carcinoma to being a marker of poor prognosis in Non-WNT/Non-SHH medulloblastoma." (PMID 36383254, 2023).
colorectal cancer (3 papers, 2021 to 2022). A primary or metastatic malignant neoplasm that affects the colon or rectum. "A novel risk locus at 4q32.2, located between the Nuclear Assembly Factor 1 (NAF1) and Follistatin Like 5 (FSTL5) genes, was associated with increased risk of developing colorectal cancer (CRC), with SNP rs17042479 being the most associated." (PMID 36067202, 2022). "By contrast, FSTL5 correlates with a poor prognosis in medulloblastoma and colorectal cancer." (PMID 34440203, 2021). "FSTL5 is also capable of firmly entering medical practice as a potential target and predictive molecular marker for the diagnosis, treatment and prognosis of HCC and colorectal cancer." (PMID 34440203, 2021).
hepatocellular carcinoma (3 papers, 2021 to 2023). A malignant tumor that arises from hepatocytes. "In hepatocellular carcinoma, FSTL5 expression inhibits the HCC growth in vitro by inducing apoptosis." (PMID 34425560, 2021).
glioma (2 papers, 2017 to 2020). A benign or malignant brain and spinal cord tumor that arises from glial cells (astrocytes, oligodendrocytes, ependymal cells). "Of note, XIST showed lower expression levels in DA tumors (versus some AA and GBM), while FSTL5 and SFRP2 expression was greater in DA vs AA gliomas." (PMID 32647207, 2020). "FSTL5, HCN1, TMEM132D, TRHDE and KRT222 showed the strongest expression correlation with other genes in the co-expression network of glioma tissues." (PMID 29046615, 2017).
breast carcinoma (1 paper, 2023). "BMP7, GDF15, BMP5, SMAD6 and FSTL5 were highly expressed in the ER positive breast cancer cells (MCF-7 cells), while the expressions of TGFBR2, FSTL1 and NOG were reduced in this cohort." (PMID 37333824, 2023).
colon cancer (1 paper, 2022). "We analyzed the promoter activity of NAF1 and FSTL5 in the three colon cancer cell lines Caco2, DLD-1 and SW480 in a promoter reporter gene assay." (PMID 36067202, 2022). "The results of the promoter reporter assay demonstrated that the FSTL5 promoter, FSTL5pro showed a slightly higher reporter gene activity in the two colon cancer cell lines DLD-1 and SW480 compared to background (the promoter-less pGL4.10 luciferase reporter plasmid)." (PMID 36067202, 2022). "The FSTL5 promoter was also more active than the pGL4.10 luciferase reporter plasmid in the two colon cancer cell lines DLD-1 and SW480, but not in Caco2 cells." (PMID 36067202, 2022). "The promoter activity analysis revealed that the FSTL5 promoter was not nearly as active in the three colon cancer cell lines as the NAF1 promoter." (PMID 36067202, 2022).
glioblastoma (1 paper, 2016). The most malignant astrocytic tumor (WHO grade IV). "For glioblastoma, in the module of tumor proliferation and progression, the hub FSTL5, as a candidate gene for tumor-suppressor, encodes a secretory glycoprotein and its expression level is highly correlated with tumor size." (PMID 27349736, 2016).
liver cancer (1 paper, 2018). An epithelial or non-epithelial malignant neoplasm that arises from the liver. "FSTL5 expression was determined by immunohistochemistry staining in a liver cancer tissue microarray (TMA) and the correlation between FSTL5 and the prognosis of HCC patients was analysed." (PMID 30255547, 2018). "This is the first study to demonstrate that FSTL5 could inhibit the xenograft tumor growth of liver cancer by promoting HCC apoptosis, rather than influencing cell cycle." (PMID 30255547, 2018).
myopia (1 paper, 2026). "Our meta-analysis identified seven novel suggestive loci associated with myopia progression, including FSTL5 on 4q32.2, SMARCA2 on 9p24.3, CCDC3 on 10p13, GALNT6/ACVR1B on 12q13.13, CRY1 on 12q23.3, ULK2 on 17p11.2, and MYL4/EFCAB13-DT on 17q21.32." (PMID 42094695, 2026).
neuroendocrine tumors (1 paper, 2020). "Among these, known biomarkers for MB (FSTL5), and other tumor types such as neuroendocrine tumors (ENO2, FMOD, ART3, COL6A3) and PIP, were found to be significantly up-regulated (dark green)." (PMID 32466393, 2020).
Talipes equinovarus (1 paper, 2023). Talipes equinovarus (also called clubfoot) typically has four main components: inversion and adduction of the forefoot; inversion of the heel and hindfoot; equinus (limitation of extension) of the ankle and subtalar joint; and internal rotation of the leg. "This suggests that in the pathogenesis of idiopathic talipes equinovarus, FSTL5 mutations affect other cell lines such as neural cells." (PMID 37964341, 2023).
tumor (9 papers, 2016 to 2026). "Nevertheless, FSTL5 expression was significantly associated with tumor size (P = 0.0024), TNM stage (P < 0.0001), and histological grade (P = 0.0037)." (PMID 30255547, 2018). "Moreover, FSTL5 expression was associated with tumor node metastasis (TNM) stage in patients with HCC." (PMID 30255547, 2018). "Proteome profiling identified characteristic tumor markers, including FSTL5, ART3, and FMOD, and revealed a strong prevalence of anti-inflammatory and tumor-promoting proteins characteristic for alternatively polarized myeloid cells in MB samples." (PMID 32466393, 2020). "The proportion of patients with HCC with downregulated FSTL5 expression in the tumor tissue was 94.4% (170/180 cases)." (PMID 30255547, 2018). "Further proliferation assay, colony formation assay, flow cytometry, and xenograft tumor model were performed to investigate the bioeffects of FSTL5 in HCC in vitro and in vivo." (PMID 30255547, 2018). "FSTL5 overexpression also decreased tumor volume and weight of Bel7404 cell xenografts by 44.1% and 51.4%, respectively; tumor volume: control: 397.2 ± 106.1 mm3 vs FSTL5: 222 ± 109.7 mm3; and tumor weight: control: 0.321 ± 0.074 g vs FSTL5: 0.156 ± 0.026 g)." (PMID 30255547, 2018). "Out of 26 cases, the proportion of patients with HCC with downregulated expression of FSTL5 mRNA in the tumor tissue was 69.2% (18/26 cases)." (PMID 30255547, 2018). "Furthermore, we explored the biological effect and underlying mechanism of FSTL5 on HCC growth with proliferation assay, colony formation assay, flow cytometry, western blotting, and xenograft tumor model in vitro and in vivo." (PMID 30255547, 2018). "The integrated Group 4 tumor datasets (n = 5) produced 9 clusters and represented 3 major groups: “MYC-driven,” “FSTL5-driven,” and “UBC-like” according to their transcriptional programs." (PMID 39659836, 2024). "Meanwhile, FSTL5 mRNA expression in HCC patient tissue obtained from West China Hospital was determined with qPCR and the result showed that FSTL5 mRNA expression in tumor tissues was also downregulated (n = 26, *P < 0.05)." (PMID 30255547, 2018). "We found that FSTL5 expression was downregulated in HCC tissues and positively correlated with the prognosis of patients with HCC at tumor node metastasis stage I/II." (PMID 30255547, 2018). "In fact, researchers have found that proteomic analysis identified typical tumor markers, including FSTL5, ART3, and FMOD, and revealed the prevalence of anti-inflammatory and tumor-promoting proteins that are characteristic of myeloid cells in CSF from patients with MB." (PMID 34977115, 2021). "According to the IHC of the liver TMA, FSTL5 expression in tumor tissues was downregulated related to normal liver tissues (n = 180, **P < 0.01)." (PMID 30255547, 2018). "Subcutaneous tumor paraffin section IHC results showed that PCNA staining in the FSTL5 group and control group were not significantly different (n = 3), and FSTL5 upregulated levels of Cleaved Caspase‐3." (PMID 30255547, 2018). "FSTL5 overexpression remarkably decreased tumor volume and weight of SMMC7721 cell xenografts by 53.1% and 46%, respectively; tumor volume: control: 1357 ± 434.9 mm3 vs FSTL5: 636.6 ± 102.7 mm3; and tumor weight: control: 0.815 ± 0.104 g vs FSTL5: 0.44 ± 0.04 g)." (PMID 30255547, 2018).
cancer (5 papers, 2018 to 2024). A tumor composed of atypical neoplastic, often pleomorphic cells that invade other tissues. "As secreted follistatin-module-containing glycoproteins, several FSLT members, covering FSTL1 and FSTL5, have been discovered to participate in cancer cell growth, stemness, chemoresistance, invasion, and migration." (PMID 34555811, 2021). "Consistent with the fact that FSTL5 mutations are often accompanied by YAP1 activation, the combination of XPO1 inhibitor and VP significantly inhibited the proliferation of these resistant KRAS/FSTL5 double mutant cancer cells." (PMID 33178014, 2020).
FSTL5 also shares sentences with these, for which no sentence is quoted: gastric cancer (1 paper); glaucoma (1); liver cirrhosis (1); osteoporosis (1); schizophrenia (1); Theileriosis (1).